IFNG (interferon gamma)
Diseases named in the same sentence as IFNG in open-access papers (continued):
Sharing a sentence is not in itself a finding about the gene and the disease.
tumor (continued). "Therefore, the tumor-site-specific activation of the PD-1/PD-L1 pathway is determined by localized induction of PD-L1 by IFNG, which indicates that higher CTL releasing IFNG and higher expression of PD-L1 are signs of impaired antitumor immune response caused by dysfunctional T-cells." (PMID 33163194, 2020). "Furthermore, Vδ2Vγ9 T cells possess the characteristics of self-activation and release the Th1-type cytokine interferon gamma (IFN-γ) and other cytotoxic cytokines, such as tumor necrosis factor (TNF), perforin, and granzymes (granzyme A and B), to eliminate tumor cells." (PMID 32849498, 2020). "Likewise, we found, in B16F10 tumours, that a significant percentage of Nrp-1+PD-1hi CD8+ TIL strongly expressed granzyme B and cell proliferation marker Ki-67, and secreted high levels of IFNγ." (PMID 31350404, 2019). "While we did not observe a significant effect of JAK1 deficiency on IFNγ-mediated upregulation of MHC I in our model, JAK1 was shown to be required for expression of MHC II that can mediate tumor and self-antigen presentation in non-professional antigen presenting cells." (PMID 31552026, 2019). "Impaired IFNγ response signaling in tumor cells may explain the absence of PD-L1 expression on TC in the context of an activated immune infiltrate as represented by high PD-L1 IC positivity." (PMID 31125352, 2019). "We found a significantly lower IFNγ response signature expression in TC negative versus TC positive tumors, suggesting an inability of the tumor cells to upregulate PD-L1 in the presence of an active and IFNγ producing immune infiltrate as is represented by expression of the Teff signature." (PMID 31125352, 2019). "In addition, increased IFNγ-expressing CD8+ cells in tumor tissues suggests that lycopene may disrupt the functions of PD-1 and PD-L1 to reduce tumor escaping from the immune system." (PMID 30948928, 2019). "Tumour interacting NK cells did not produce IFNγ in the absence of IL2." (PMID 31595191, 2019). "IL-10 and TGF-β reduce synthesis of interferon-gamma (IFN-γ) and TNF-α by pro-inflammatory CD4 T cells, thus, lower tumor-specific cytotoxicity of CD8 cells, inhibit the main functions of dendritic cells and NK cells and this way induce tolerance to tumor cells." (PMID 31717542, 2019). "Interestingly, our results showed that a mixed IL-9/IFNγ secreting T cell response was induced when the tumour bearing mice received a low dose of DCG spore (1 × 108 CFU/kg), while a strong IFNγ response was elicited with a high dosage of DCG spore (3 × 108 CFU/kg)." (PMID 31183361, 2019). "Even more surprising considering their tumor-permissive properties, the CD103−CD11b+ DC subset induces CD4+ T cells to express high TH1- and TH17-family cytokines and transcription factors, including a substantial IFNγ+IL17+ population, which co-expresses IL-10." (PMID 30926808, 2019). "CD8+ T cells recognize specific tumor antigens presented via major histocompatibility complex class I (MHC-I) molecules, triggering the secretion of cytotoxic molecules and effector cytokines [e.g. interferon gamma (IFN-γ)] that result in the immune killing of the target cell." (PMID 31535086, 2019). "In animal models, interferon-gamma induced upregulation of PD-L1 drove secondary resistance to VEGF-blockade while concurrent anti-angiogenic therapy and PD-L1 inhibition induced formation of high endothelial venules, which facilitated T-cell infiltration and enhanced anti-tumor activity." (PMID 31295966, 2019). "In evaluable tumor biopsies, MEDI0680 showed intratumoral pharmacodynamic activity as evidenced by the induction of CD8+ T-cell infiltration and/or expansion and increases of IFNG and IFNγ-inducible gene expression consistent with the mechanisms of action of anti-PD-1 blocking agents." (PMID 31439037, 2019).
tumor (continued). "The levels of two pro-inflammatory cytokines, interferon gamma (IFN-γ) and tumor necrosis factor alpha (TNF-α), are significantly reduced in tumor microenvironments containing CD8+LAG-3+PD-1+ T-cells compared with those in the tumor milieu containing LAG-3+ or PD-1+CD8+ T-cells." (PMID 30271341, 2018). "Interestingly, IFNγ blockade, but not T cell deficiency, reversed the effects of LNT treatments on tumor blood vessels." (PMID 30373628, 2018). "Briefly, during the experiment, dCAR-T cells could release significant levels of cytokines only in the presence of cognate tumor cells expressing both CEA and MSLN, including 751 pg/mL IL-2, 9297 pg/mL IFNγ, 1777 pg/mL TNFα, 732 pg/mL IL-4, 8991 pg/mL IL-13, and 99 pg/mL IL-15." (PMID 30103775, 2018). "The IFNG locus demonstrated a demethylated pattern in the primary tumours (at TUR-B) of pT0 patients (complete NAC-responders) and in non-invasive tumours (pTa-Tis) compared to in primary tumours with muscle invasive tumour outcomes post-RC (pT2) (p < 0.0001 resp." (PMID 30075815, 2018). "Likewise, overnight rest in fresh media did not restore tumor NK cell degranulation or IFNγ production, suggesting that functional impairment was not due to a reversible metabolic restriction or competition for nutrients in coculture." (PMID 29867983, 2018). "Our data demonstrate that chronic TGFβ imprinting in conjunction with activation and IL-2 has opposite effects of acute TGFβ exposure (6 h to 3 days), driving NK cells to produce more IFNγ and TNFα upon tumor target and PHA stimulation than NK cells that were not TGFβ imprinted." (PMID 30400618, 2018). "In this study WT and PLT2 mice exhibited similar profiles for NK cells and for total CD8+ T cells as well as CD8+IFNγ+ T cells, indicating that the NK and CD8+ T cell phenotype might not be involved in the loss of anti-tumor activity in the PLT2 mice." (PMID 30383838, 2018). "Thus, somewhat counterintuitively, TIL secretion of IFNγ can itself induce a negative feedback loop and adaptive resistance by upregulating PD-L1 on tumor cells." (PMID 30497521, 2018). "Recently Kammertoens et al25 showed that responsiveness of myeloid cells and other haematopoietic cells to IFNγ was not sufficient for tumor regression induced by IFNγ, whereas responsiveness of endothelial cells to IFNγ was necessary and sufficient for tumor regression." (PMID 30039553, 2018). "Bortezomib administration increased IFNγ and granzyme-B expression on Vβ8.1/2+CD8+T cells in tumor-bearing mice even in the presence of IL-12 and IL-15 neutralization antibody treatments, and restored them to the levels comparable to tumor-bearing mice treated with bortezomib only." (PMID 28052005, 2017). "Addition to the immunomodulatory effects of IDO1 on tumour cells, we speculated that IDC cells (via IFNγ) -induced IDO1 in ECs could catalyse the oxidation of L-tryptophan into kynurenine, which results in a reduction in the availability of tryptophan for the TSP1 synthesis by ECs." (PMID 29156701, 2017). "Alternatively, the facts that antitumor CTL rely on IL-2 and IFNγ for tumor rejection and that pancreatic HNT CD4+ T cells were able here to secrete IFNγ and IL-2 in response to antigen suggest that these cytokines may be involved in providing help to clone 4 CD8+ T cells." (PMID 29403481, 2017). "Thus, we concluded that IFNγ, TNFα, and IL-10 did not alter the expression of B7x in human and murine tumor cell lines." (PMID 29137299, 2017). "In bortezomib-treated 4T1HA tumor-bearing mice, CD4+T-cells showed increased IL-2 production, CD11c+ dendritic cells showed increased IL-12 and IL-15 production, and HA-specific activated CD8+T-cells showed enhanced expression of IFNγ, granzyme-B and transcription factor eomesodermin." (PMID 28052005, 2017).
tumor (continued). "Taken together with our observation that, in contrast to IFNG, none of the type I IFN genes associated with a longer OS is expressed at significant levels by TAMs, TATs or tumor cells it is conceivable that upregulation of the IFN target genes of signature B is due to activated IFNγ signaling." (PMID 28327095, 2017). "In addition to the in vitro experiments demonstrating that DFT1 cells upregulate MHC class I in response to IFNγ, DFT1 cells in tumour biopsies have been found that express β2m when clusters of CD3-positive leukocytes are adjacent, implying a response to IFNγ or other inflammatory cytokines." (PMID 28695294, 2017). "Regression could result from the elevated IFNγ converting the TME to a Th1 microenvironment and enhancing the activity of other effector cells, or from promoting epitope spreading, which could expand novel tumor reactive T cell clones." (PMID 28969075, 2017). "This enabled a broad study across tumor types demonstrating opposing effects of IFNγ, a finding that may not have been evident in other studies that focus on a single tumor type or modulation of a single surface ligand." (PMID 28428785, 2017). "Alternatively, the decreased IFNγ may lead to a low level of programmed death-ligand 1 expression on tumor cells, contributing to the reverse of the exhaustion of CD8+ T cells in the tumor microenvironment because IFNγ is a key factor that stimulates programmed death-ligand 1 expression." (PMID 28861089, 2017). "More specifically, tumor-specific T cell response to tumor-associated antigens MAGE-6 and EphA2 is characterized by a predominance of T cells synthesizing IL5 and IL4, together with reduced levels or a complete absence of T lymphocytes expressing IFNγ." (PMID 28409322, 2017). "Treating big tumors with autologous human T cells that do not survive for long inside the mice makes very difficult to observe an effect, as illustrated by the fact that adoptive cell transfer and intratumoral IFNγ injection was not able to reduce the tumor growth at all." (PMID 28986561, 2017). "Accordingly, we analyse the cytokine expression changes (more than 1.5 log2, 2.8 fold, p < 0.05, t-test) between No take and Take tumours and found a large series of chemokine/cytokine overexpressed in the No take samples, among them IFNG, CXCL13, CXCl9, CXCl11, CXCL10 and CCL5." (PMID 28588211, 2017). "In response to virus or HER2-p63 restimulation, a five- to tenfold increase in the magnitude of IFNγ+ T cells was found in mice treated with MVA-BN-HER2 compared to tumor-bearing mice that received no treatment (control) or CTLA-4 blockade alone, as shown by the relative size of the pie charts." (PMID 26961085, 2016). "It has been suggested that TGF-β may reduce tumor lysis mediated by NK cells and stimulate the production of proinflammatory cytokines such as tumor necrosis factor alpha (TNF-α) and interferon gamma (IFN-γ)." (PMID 26983546, 2016). "However, based on the significant increase in infiltration of macrophages and NK cells into the tumor microenvironment in mice treated with Ad.EPCR, it is likely that macrophages and NK cells are the primary sources of the production of TNFα and IFNγ, respectively." (PMID 27833109, 2016). "Similarly, freshly purified total T-cells from the spleens of CY+TLRa-treated mice also showed an absence of anti-tumor impact in vitro unless CpG+IFNγ were also added to culture (image 11 vs 13 ***p < 0.0001)." (PMID 27341020, 2016). "However, the simulation results suggest that the effect of IFNG release within the tumor microenvironment is saturated, therefore further increases in IFNG will not reduce tumor growth." (PMID 28101055, 2016). "Interestingly, SKIL of patient B-9 produced IFNγ upon co-culture with tumor protein and not with HLA-A*02:01-binding peptides, indicating that T cells recognized different epitopes." (PMID 26861670, 2016). "During this phase, activated T cells and IFNγ manage to limit tumor growth without removing it." (PMID 28018902, 2016).
tumor (continued). "As expected, tumor-derived TGF-β1 established a systemic immunosuppressive environment that was represented by an increase of the CD4+Gr11b+ T-cell population and a decrease of the activated subpopulation of CD4+CD44+CD62L– T cells in lungs and spleens and CD8+IFNγ+ T cells in spleens." (PMID 27036297, 2016). "To test the hypothesis that CY+TLRa tumor rejection depended upon a T1-type immune response, we transferred IFNγ KO rather than WT T-cells." (PMID 27341020, 2016). "While IFNγ could influence immune recognition at a variety of levels, one now obvious effect could be by correcting the disparity in epitope repertoires between those displayed by APC and tumor." (PMID 26885372, 2016). "Therefore, although CXCR6/CXCL16 interactions enhance beneficial IFNγ responses from iNKT cells, there could be additional mediators or processes regulated by CXCR6/CXCL16 interactions that contribute to tumor control." (PMID 27471636, 2016). "Notably, also CD8+ T-cell depletion partly reversed the cDC2 vaccination effect, which is in accordance with the enhanced activation state (as shown by enhanced IFNγ production) by these cells in tumours from vaccinated versus non-vaccinated mice." (PMID 28008905, 2016). "Notably, cDC2 vaccination does not increase the number of SIINFEKL-specific CTL in tumours compared with non-vaccinated mice, but increases the IFNγ production by these cells, explaining the partial contribution of CD8+ T cells to the success of vaccination." (PMID 28008905, 2016). "However, when PDX tumours were freshly resected, sectioned and grown ex vivo as cultured tissue slices, in the presence or absence of IFNγ, only the PT2 PDX model (anti-PD-1 responder) upregulated HLA-DR." (PMID 26822383, 2016). "While the specific biochemical details may be different in reality, the dependence on IFNG represents a negative feedback mechanism whereby an ongoing anti-tumor immune response inhibits the cell-mediated cytotoxic activity." (PMID 28101055, 2016). "In addition, CD4+ T helper cells may function as effector cells either by the local production of cytokines (IFNγ and IL2) that curtail tumour growth or trigger the release of cytotoxic mediators towards MHC II tumour cells." (PMID 26081906, 2015). "In addition, rtPCR analysis of IFNg and CD8 mRNA expression in treated tumours revealed a significant fourfold increase in IFNg levels in responding tumours, while IFNg levels in non-responding tumours did not change." (PMID 25628149, 2015). "IL-15 KO/MT spleen or tumor CD8 T cells produced little to no IFNγ (data not shown)." (PMID 25879689, 2015). "The number of activated (CD25+ CD62Llow) and IFNγ-producing OTII CD4 T cells was significantly greater in the 12-month-old CR mice than 12-month-old ad libitum mice (AL-LRD) and was comparable with young 2-month-old mice (2MO), verifying the findings from the tumor setting." (PMID 24682539, 2014). "Since expanded γδT cells retain the capacity to secrete pro-inflammatory cytokines (IFNγ, TNFα) and to express, albeit at reduced levels, lymph node-homing markers (CCR7, CD62L), the infusion of tumor-antigen-loaded γδT cells may be followed by a single treatment with zoledronate." (PMID 25101086, 2014). "Groups receiving vaccination (alone or in combination with surgery) had noticeably smaller tumors on the day of surgery and a significantly higher proportion of interferon gamma (IFN-γ) expressing tumor-specific CD8 T cells when compared to non-vaccinated groups one week after vaccination." (PMID 25186961, 2014). "In addition to 51Cr release experiments, the killing of SKBR3 tumor cells was evidenced by their Annexin V+ 7-AAD− profile, while the state of iNKT cell activation was evaluated by CD107a expression, and secretion of TNFα and IFNγ." (PMID 23242316, 2013). "Therefore, despite the apparent increase in CTL and NK cells in hiEBVaGCs, the activated IFNG signaling may counteract this response through IDO1 mediated Trp depletion; allowing tumor survival." (PMID 23671415, 2013).
tumor (continued). "No anti-tumor effector cells or cytokines that potentiate anti-tumor immunity (i.e., IFNγ and IL-2) could be detected in spleens of mice injected with fibrosarcoma cells transfected with IL-1β or ssIL-1β or with the violent parental cells." (PMID 23847618, 2013). "In addition, CD8+ CTL express IFNγ which can induce apoptosis of certain tumors and/or influence hematopoietic and non-hematopoietic cells within the tumor microenvironment to affect tumor growth." (PMID 23060881, 2012). "Interestingly, IFNγ has previously been shown to be essential for T cell-mediated tumor destruction through non-hematopoietic, stromal cells such as endothelial cells." (PMID 24213314, 2012). "Also, IL-12 stimulate Th1 and CD8+ to secrete IFNγ which in turn promotes a wide array of host responses to tumors, including the activation of CD8+ cells and the recruitment of NK cells within the tumor." (PMID 22046194, 2011). "Five mouse-specific cytokines were significantly (P=0.03) higher expressed in VEGFA165 tumours compared with control tumours: interleukin 5 (IL5), IL7, chemokine (C-X-C motif) ligand 9 (CXCL9, MIG), colony-stimulating factor 1 (macrophage) (MCSF) and interferonγ (IFNG)." (PMID 22045186, 2011). "Liver and tumor tissues from the ablation sites and from distant sites were collected at various time points following LA and changes in CD3+ T cells and Kupffer cells (F4/80 marker) infiltration and the expression of interferon gamma (IFNγ) were investigated by immunohistochemistry and ELISpot." (PMID 21619693, 2011). "Moreover, increased activation of splenocytes and tumor infiltrating lymphocytes was reported in ex vivo IFNγ ELISPOT without antigen restimulation." (PMID 22242035, 2011). "Similarly to the IFNγ/STAT1 signaling, STAT3 and IL-10 can form a positively regulatory loop to promote tumor progression and metastasis through sustaining immunosuppressive environment in tumor tissue." (PMID 21931823, 2011). "Although the precise mechanism is required further investigation, tumor cell-induced STAT3 activation may largely be responsible for the suppression of IFNγ/STAT1 signaling and Th1 responses in mice treated with the TLR4/9 agonist complex after tumor cell inoculation." (PMID 21931823, 2011). "Interestingly, tumor-specific effector cells isolated from TDLN but not from the spleen or peripheral blood secreted a higher amount of IFNγ (between days 3 and 7 after treatment) as compared to cells obtained following surgical resection." (PMID 22242035, 2011). "Notably, neither loading of tumor cells with α-GC nor addition of IL-12 were sufficient to induce the IFNγ production of NKT cells in contact to prostate tumor cells." (PMID 24212972, 2011). "While CSE caused a decrease of intracellular interferon gamma (IFN-γ) production and increase of IL-10 production by NK cells in all cases, the effects were not significant (IFN-γ: 10.4% vs. 5.6%, n = 5, p = 0.09, IL-10: 1.7% vs 11.5%, n = 5, p = 0.1) upon tumour challenge." (PMID 20107494, 2010). "Moreover tumor cells not coated with Rituximab or treated with irrelevant antibody such as Herceptin which does not bind to Raji cells were not lysed by IFNγ primed macrophages." (PMID 19148288, 2009). "In most cases of NPC, the dense infiltration of lymphocytes is observed in the tumor site, and EBV-associated viral antigens in tumor cells are presented for lymphocyte recognition, nevertheless IFNγ fails to exert its intended anti-viral and anti-tumor effects in the patients with NPC." (PMID 19948041, 2009). "Rituximab-coated Raji tumor cells were then labeled with mouse anti-human CD37 antibody (a B cell-specific cell surface marker) followed by goat anti-mouse Alexa Fluor 594 (red fluorescence) and IFNγ primed macrophages were stained with FITC-phalloidin (green fluorescence)." (PMID 19148288, 2009).